NUTF2P3 (nuclear transport factor 2 pseudogene 3)
Gene: Processed pseudogene on chromosome 9 (77,580,245 to 77,580,628, forward strand). Ensembl gene ENSG00000228248.
Diseases named in the same sentence as NUTF2P3 in open-access papers:
NUTF2P3 is named in the same sentence as 4 diseases in open-access papers, as found by Europe PMC text mining. Sharing a sentence is not in itself a finding about the gene and the disease. The quoted sentences say what the papers report.
pancreatic cancer (10 papers, 2016 to 2025). "This study found that downregulation of NUTF2P3-001 using NUTF2P3-001-siRNA significantly reduced the viability of pancreatic cancer cells." (PMID 40861273, 2025). "Overexpression of NUTF2P3-001 in pancreatic cancer and chronic pancreatitis tissues is positively correlated with cancer cell characteristics, such as tumor size and distant metastasis." (PMID 34489556, 2022). "After downregulated with NUTF2P3-001-siRNA, the viability of pancreatic cancer cell was significantly reduced." (PMID 26755660, 2016). "On the other hand, the miR-3923 inhibition remarkably rescued the suppression of NUTF2P3-001-siRNA on pancreatic cancer cell." (PMID 26755660, 2016). "Since lncRNA-NUTF2P3-001 was upregulated in pancreatic cancer samples, we downregulated lncRNA-NUTF2P3-001 with lncRNA-NUTF2P3-001-siRNA (NUTF2P3-001-siRNA) to further identify its functional roles in pancreatic cell lines PANC-1 and BXPC-3." (PMID 26755660, 2016). "Additionally, the proliferation of pancreatic cancer cells was markedly inhibited following treatment with lentivirus containing NUTF2P3-001-siRNA (LV-NUTF2P3-001-siRNA)." (PMID 40861273, 2025). "In addition, downregulation of NUTF2P3-001 inhibits the viability, proliferation, and invasion of pancreatic cancer cells and contributes to a decrease in KRAS expression." (PMID 34489556, 2022). "Moreover, the proliferative ability of pancreatic cancer cell was remarkably inhibited after treated with lentivirus containing NUTF2P3-001-siRNA (LV-NUTF2P3-001-siRNA)." (PMID 26755660, 2016). "Furthermore, the present study displayed that miR-3923 overexpression significantly inhibited proliferation and invasion of pancreatic cancer cell both in vivo and in vitro, which dramatically simulating the suppressive effects of NUTF2P3-001-siRNA." (PMID 26755660, 2016). "More importantly, downregulation of KRAS and its downstream proteins, p-AKT and p-ERK, were detected after NUTF2P3-001-siRNA transfection, indicating that the lncRNA-NUTF2P3-001 acted as promoter in pancreatic cancer in vitro and might play a role via regulating KRAS and its downstream pathways." (PMID 26755660, 2016). "A recent study has demonstrated that lncRNA NUTF2P3-001 acts as a ceRNA to communicate with KRAS by competitively binding to hsa-mir-3923, and the up-regulation of NUTF2P3-001 reverses the suppressive effect of hsa-mir-3923 on KRAS, leading to the proliferation and invasion of pancreatic cancer." (PMID 30261893, 2018). "In pancreatic cancer, the expression of miR-646 and miR-548 is correlated with clinicopathological indicators such as TNM stage and overall survival (OS), and hypoxia-induced lncRNA NUTF2P3-001 overexpression also indicates advanced TNM stage and shorter survival time of patients." (PMID 32014012, 2020).
NUTF2P3 also shares sentences with these, for which no sentence is quoted: cancer (1 paper); chronic pancreatitis (1); tumor (1).